SNX16 (sorting nexin 16)
Description:
May be involved in several stages of intracellular trafficking. Plays a role in protein transport from early to late endosomes. Plays a role in protein transport to the lysosome. Promotes degradation of EGFR after EGF signaling. Plays a role in intracellular transport of vesicular stomatitis virus nucleocapsids from the endosome to the cytoplasm.
Tractability: Antibody: UniProt places it where antibodies can reach, with medium confidence. PROTAC: ubiquitination databases record sites on it; its protein half-life has been measured.
Gene: Protein-coding gene on chromosome 8 (81,799,581 to 81,842,866, reverse strand). Ensembl gene ENSG00000104497.
Subcellular location: Early endosome membrane; Late endosome membrane; Cytoplasm; Lysosome
Subcellular location (Human Protein Atlas): Plasma membrane; Vesicles
Gene Ontology:
Molecular function: identical protein binding; phosphatidylinositol binding
Biological process: early endosome to late endosome transport; endosome to lysosome transport; protein targeting to lysosome; receptor recycling
Cellular component: early endosome; endosome membrane; late endosome; cytoplasm; early endosome membrane; late endosome membrane; lysosome
Genetic constraint (gnomAD): Loss-of-function variants: 24 observed, 23.98 expected, observed/expected ratio (o/e) 1, 90% interval 0.72 to 1.41. The upper end of that interval is the gene's LOEUF score, 1.41, which puts it in group 5 of 6, group 1 being the genes least tolerant of losing a copy. Missense variants: 266 observed, 306.01 expected, observed/expected ratio (o/e) 0.87, 90% interval 0.79 to 0.96. Synonymous variants: 104 observed, 100.03 expected, observed/expected ratio (o/e) 1.04, 90% interval 0.89 to 1.22.
Homologues: Orthologues: chimpanzee SNX16 (99% identical), macaque SNX16 (98% identical), guinea pig SNX16 (92% identical), pig SNX16 (92% identical), rat Snx16 (85% identical), mouse Snx16 (84% identical), rabbit SNX16 (69% identical), tropical clawed frog snx16 (64% identical), zebrafish snx16 (52% identical), Drosophila melanogaster Snx16 (30% identical). Paralogues in human: PXK (20% identical).
Diseases named in the same sentence as SNX16 in open-access papers:
SNX16 is named in the same sentence as 32 diseases in open-access papers, as found by Europe PMC text mining. Sharing a sentence is not in itself a finding about the gene and the disease. The quoted sentences say what the papers report.
hepatocellular carcinoma (5 papers, 2022 to 2025). A malignant tumor that arises from hepatocytes. "LncRNA GSEC encourages the progression of hepatocellular carcinoma by targeting the miR-101-3p/SNX16/PAPOLG axis." (PMID 37842058, 2023). "SNX16 has previously been described as acting as an oncogene in hepatocellular carcinoma, promoting tumor aggressiveness through the EGFR–AKT pathway, and its inhibition has been proposed to offer therapeutic benefits by blocking tumor cell proliferation and invasion." (PMID 40863222, 2025). "However, SNX16's biological impact and molecular underpinnings in hepatocellular carcinoma (HCC) remain elusive." (PMID 38849490, 2024). "Additionally, several research reported GSEC could promote the malignant process of triple-negative breast cancer and hepatocellular carcinoma via the GSEC/miR-202-5p/AXL axis and the GSEC/miR-101-3p/SNX16/PAPOLG axis, respectively." (PMID 38409243, 2024).
colorectal cancer (3 papers, 2020 to 2022). A primary or metastatic malignant neoplasm that affects the colon or rectum. "In a recent study, SNX16 was highly expressed in colorectal cancer and activated the c-Myc signaling pathway by upregulating eEF1A2, thereby promoting colorectal cancer development." (PMID 35482720, 2022). "For example, SNX16 activates c-Myc signaling by inhibiting ubiquitin-mediated proteasomal degradation of eukaryotic translation elongation factor 1A2 in colorectal cancer development." (PMID 33647065, 2021). "However, the function of SNX16 has not yet been investigated in colorectal cancer (CRC)." (PMID 31876369, 2020).
breast carcinoma (2 papers, 2013 to 2020). "We initially investigated the distribution of ectopic SNX16 (Flag- or GFP-tagged) in MCF-7 which is a commonly used cell line derived from human breast cancer." (PMID 25408875, 2013). "Furthermore, ectopic expression of SNX16 is able to reduce the in vivo tumorigenic activity of a breast cancer cell line in the mouse model." (PMID 25408875, 2013). "However, SNX16 was also reported to stimulate EGF receptor degradation in COS‐7 cells and a previous study has shown that SNX16 overexpression in MCF‐7 breast cancer cell lines could decrease migration and tumor size in a mouse xenograft model." (PMID 31876369, 2020).
arteriosclerosis (1 paper, 2020). A vascular disorder characterized by thickening and hardening of the walls of the arteries. "However, SNX16 overexpression in late endosomes inhibit cholesterol transport, accumulate cholesterol, and may cause arteriosclerosis." (PMID 32012743, 2020). "However, since these results and the current literature do not reveal a direct molecular or clinical link between SNX16 and arteriosclerosis in patients with OSA, this question remains to be explored." (PMID 32012743, 2020).
bladder cancer (1 paper, 2020). "It is reported that SNX16 was overexpressed in the blood cells of bladder cancer patients and ovarian cancer tissues." (PMID 31876369, 2020). "SNX16 was found to be overexpressed in the blood cells of bladder cancer patients." (PMID 31876369, 2020).
cervical cancer (1 paper, 2013). A primary or metastatic malignant neoplasm involving the cervix. "We found that the cell cortex localization of SNX16 is clearly detected in all cell lines examined, which include a cervical cancer cell line (Hela), liver cancer cell lines (HepG2 and Bel7402) and lung cancer cell lines (GLC-82 and NCI-H460)." (PMID 25408875, 2013).
colorectal tumors (1 paper, 2020). "In public datasets analysis, we found a significant increase of SNX16 mRNA level in primary colorectal tumors as compared to their normal mucosa." (PMID 31876369, 2020).
diabetes (1 paper, 2020). "Additionally, although the analysis in the OSA group has denied the correlation between age, sex, smoking status, hypertension, diabetes, dyslipidemia and SNX16-Ab level, potential confounding factors in between the OSA, ACS and HA group were not completely excluded." (PMID 32012743, 2020).
glaucoma (1 paper, 2009). Increased pressure in the eyeball due to obstruction of the outflow of aqueous humor. "The objective of this study was to investigate association of several genes that have not been subject to an association study with glaucoma cases so far but might be functionally linked to glaucoma pathogenesis (RDX, SNX16, MFN1, MFN2, PARL, SOD2)." (PMID 19754948, 2009).
influenza (1 paper, 2022). An acute viral infection of the respiratory tract, occurring in isolated cases, in epidemics, or in pandemics; it is caused by serologically different strains of viruses (influenzaviruses) designated A, B, and C, has a 3-day incubation period, and usually lasts for 3 to 10 days. "Given the critical anti-influenza function of SNX16, our study established that SNX16 could be a potential target for the development of antiviral drugs." (PMID 35458555, 2022).
leukemia (1 paper, 2010). A malignant (clonal) hematologic disorder, involving hematopoietic stem cells and characterized by the presence of primitive or atypical myeloid or lymphoid cells in the bone marrow and the blood.
melanoma (1 paper, 2020). A malignant, usually aggressive tumor composed of atypical, neoplastic melanocytes. "Previous studies have also suggested that SNX16 exhibited alternative splicing in certain melanoma cell lines and could interact with 32 SNPs that are known risk factors for prostate cancer." (PMID 31876369, 2020). "Previous studies have suggested that SNX16 exhibited alternative splicing in certain melanoma cell lines and could interact with 32 SNPs, which is a known risk factor for prostate cancer." (PMID 31876369, 2020).
normal tension glaucoma (1 paper, 2009). "Results suggested that genetic variation in five of the candidate genes (RDX, SNX16, OPA1, SOD2 and CYP1B1) is unlikely to confer major risk to develop normal tension glaucoma in the German population." (PMID 19754948, 2009).
Obesity (1 paper, 2024). Accumulation of substantial excess body fat. "Then, we selected 5 variants in genes previously reported to be associated with obesity, adipogenesis or linked to obesity-associated traits by genome-wide association studies (SLC25A5, AIM2, SNX16, CAMKK2 and PDE11A) for further analysis to identify candidate MOVs." (PMID 38469147, 2024).
ovarian carcinoma (1 paper, 2020). A malignant neoplasm originating from the surface ovarian epithelium. "In addition, SNX16 levels were significantly higher in ovarian cancer tissue than in normal tissues." (PMID 31876369, 2020).
tumor (5 papers, 2013 to 2025). "Sorting nexin 16 (SNX16), a member of the sorting nexin family, has been implicated in tumor development." (PMID 31876369, 2020). "Sorting nexin 16 (SNX16), a pivotal sorting nexin, emerges in tumor progression complexity, fueling research interest." (PMID 38849490, 2024). "In the meantime, the tumor‐suppressive functions of SNX16 knockdown were significantly reversed by c‐Myc overexpression." (PMID 31876369, 2020). "Reversely, overexpression of SNX16 in SW480 cells significantly promoted tumor growth by 122% and increased the tumor weight by 103% compared to the negative controls." (PMID 31876369, 2020). "Thus, our results suggested that eEF1A2 is indispensable for SNX16‐mediated tumor‐promoting functions in CRC cells." (PMID 31876369, 2020). "Ectopic expression of SNX16 reduces the migration and the tumor formation activity of MCF-7 cells." (PMID 25408875, 2013). "SNX16 and PAPOLG high expression groups were mainly enriched in tumor and immune-related pathways." (PMID 35482720, 2022). "Moreover, the result of gene set enrichment analysis suggested that SNX16 and PAPOLG were mainly enriched in tumor- and immune-related pathways." (PMID 35482720, 2022). "We found that the ectopic expression of SNX16 but not SNX2 significantly reduces the tumor formation activity of MCF-7 cells (P=0.001, 0.0002 and 0.27 for SNX16-1, SNX16-2 and SNX2 respectively)." (PMID 25408875, 2013). "The results showed that knockdown of SNX16 in HT29 cells significantly suppressed tumor growth by 57% and lowered the tumor weight by 60% compared to the negative controls." (PMID 31876369, 2020).
cancer (2 papers, 2010 to 2020). A tumor composed of atypical neoplastic, often pleomorphic cells that invade other tissues. "Hence, although SNX16 was related to cancers in various aspects, the precise expression pattern and functional roles of SNX16 in tumors remain exclusive." (PMID 31876369, 2020).
SNX16 also shares sentences with these, for which no sentence is quoted: adenocarcinoma (1 paper); cardiovascular disease (1); copy number variation (1); dyslipidemia (1); gastric cancer (1); Hypertension (1); infection (1); liver cancer (1); lung carcinoma (1); myeloma (1); prostate carcinoma (1); renal cell carcinoma (1); Spinocerebellar Ataxia 15 (1); Stroke (1); triple-negative breast carcinoma (1).